SMAD3 (SMAD family member 3)
Diseases named in the same sentence as SMAD3 in open-access papers (continued):
Sharing a sentence is not in itself a finding about the gene and the disease.
breast carcinoma (continued). "In this study, we screened in human breast cancer cells and identified the transcription factor ZNF8 as a novel protein that interacts with Smad3, which is a well‐known mediator of the TGF‐β pathway." (PMID 39225541, 2024). "The analysis showed a significant increase in the concentration of SMAD3, SMAD4, and SMAD5 in all types of breast cancer samples compared to the control." (PMID 39337574, 2024). "Consistently, chip-seq analysis regarding SMAD3 in lung cancer (NCL-H441) and breast cancer cell lines (HCC1954, MDA-MB-231) together showed that there were 3 SMAD3 binding peaks in the promoter region of TGILR." (PMID 38806480, 2024). "One recent study demonstrates that narasin inhibits tumor metastasis and growth of ERα-positive breast cancer cells, and this is through inactivation of the TGF-β/SMAD3 and IL-6/STAT3 signaling pathways." (PMID 37864240, 2023). "FOXM1 promotes EMT in breast cancer through direct binding and activation of the SLUG promoter, and it interacts with SMAD3 to sustain TGF-β-induced breast cancer metastasis." (PMID 37370117, 2023). "EW-7197 is a potent, selective, orally bioeffective TGFβ receptor ALK4/ALK5 inhibitor that can inhibit TGFβ-induced Smad2 or Smad3 phosphorylation and epithelial to mesenchymal transition (EMT) in TGFβ-treated breast cancer cells." (PMID 35794374, 2023). "SMAD3 BMPR2, XIAP, and ESR1 have also been proven to be regulated by OS in skin fibroblasts, vascular smooth-muscle cells, PC6.3 cells, and breast cancer." (PMID 35954205, 2022). "Targeting SMAD3 methylation using TAT peptides 1 and 2 dramatically inhibited breast cancer metastasis." (PMID 35085106, 2022). "It has been shown that WWOX physically binds to SMAD3 through its WW1 domain, leading to inhibition of its activity and enhanced TGF-β signaling in breast cancer cells." (PMID 36572673, 2022). "Sun and colleagues reported a direct interaction between the ICD of NOTCH4 and SMAD3 and demonstrated that this interaction attenuated TGFβ-mediated growth inhibition of MCF-7 breast cancer cells." (PMID 36970723, 2022). "Activated Smad3 promotes the transcription of PTHLH in response to TGFβ1, which is also known as a cachexia-inducing factor, in breast cancer." (PMID 35406121, 2022). "Smad3, a transcription factor, upregulates the transcription of PTHLH by binding to the proximal PTHLH promoter region in response to TGFβ1 signalling in breast cancer cells and consequently promotes bone metastasis." (PMID 35406121, 2022). "It has also been reported that S100A4 can physically and functionally interact with Smad3 to increase TGF-β-induced matrix metalloproteinase-9 expression and invasion ability in breast cancer cells." (PMID 36078170, 2022). "For example, in the metastatic breast cancer cell model MDA-MB-231, Smad2 knock-down led to a more aggressive phenotype, while Smad3 knock-down led to a lag in tumor initiation, suggesting that Smad2 and Smad3 have opposing effects on disease progression." (PMID 35858839, 2022). "Our data suggested that tRF-17-79MP9PP inhibits the THBS1-mediated TGF-β1/Smad3 pathway and the EMT related genes (MMP3, MMP-9 and N-cadherin) in breast cancer cells." (PMID 33912465, 2021). "Our results indicated that LAE inhibited TGF-β1 signaling pathway via Erk1/2 and SMAD3 in SK-BR-3, MDA-MB-231 and HCC1806 breast cancer cells." (PMID 33602253, 2021). "In this study, our data demonstrated that LAE significantly inhibits the ER− breast cancer cell migration and metastasis via the TGF-β1/Erk1/2 and TGF-β1/SMAD3 signaling pathways, accompanied by reduced intracellular H2O2 level in ER− breast cancer cells." (PMID 33602253, 2021). "In the present study, we demonstrated that LAE inhibited EMT and cell migration via Erk1/2 and SMAD3 and reducing H2O2 production in ER− breast cancer." (PMID 33602253, 2021).
breast carcinoma (continued). "In breast cancer, DHA inhibits EMT by reducing TGF-β production and decreasing phosphorylation of Smad2 and Smad3." (PMID 34539408, 2021). "In this study, our data showed that LAE significantly inhibits the ER− breast cancer cell migration and metastasis via the SMAD3 and Erk1/2 signals, accompanied by reduced intracellular H2O2 level in ER− breast cancer cells." (PMID 33602253, 2021). "Here we report for the first time that in human breast cancer, AML and embryonic cells, HIF-1 and AP-1 upregulate the expression of TGF-β, leading to the activation of Smad3 through autocrine action." (PMID 33295886, 2020). "The administration of Res suppresses the metastasis of breast cancer (under both in vitro and in vivo conditions) via the inhibition of TGF-β1 and down-regulation of Smad2 and Smad3." (PMID 32752069, 2020). "In breast cancer, TGF-β can stimulate EMT via Smad2 and Smad3 activation, leading to an increase in N-cadherin and vimentin levels, and a decrease in E-cadherin levels." (PMID 32752069, 2020). "In breast cancer cells, overexpressing ci-miRNA-191, was associated with upregulated levels of TGF-β pathway genes (TGFβ2, SMAD3, BMP4, JUN, FOS, PTGS2, CTGF, and VEGFA), thus promoting breast cancer growth and metastasis." (PMID 32942528, 2020). "In this context, it has been shown that overexpression of Smad3 suppresses cell apoptosis and promotes cell proliferation, whereas treatment with Smad3 inhibitor (SIS3) promotes apoptosis and inhibits proliferation of breast cancer cells." (PMID 33377651, 2020). "In breast cancer cells, overexpression of C/EBPβ increased the protein expression levels of TGF‐β1 and pSmad3 and repressed Smad3 expression." (PMID 30761253, 2019). "Mechanistically-wise, it was suggested that CCR2 regulates CCL2-induced breast cancer cell motility through MAPK- and Smad3-dependent mechanisms." (PMID 31350989, 2019). "In breast cancer, CCL2/CCR2 axis coordinates cells survival and motility through Smad3 and MAPK-dependent mechanisms." (PMID 31501414, 2019). "As expected, the Smad3 knockdown markedly suppressed the TGF‐β‐triggered upregulation of the mRNA and protein expression of EGFR in two breast cancer cells." (PMID 29215776, 2018). "Downregulation of Sp1 or Smad3 significantly inhibited the TGF‐β‐induced enhancement of the migration and invasion abilities of two breast cancer cells." (PMID 29215776, 2018). "C‐ets‐1 was the top candidate as this transcription factor has previously been described to synergize with SMAD3 and its expression also correlated the most with expression of TGFBR2 as well as of MET in breast cancer cell lines." (PMID 30004628, 2018). "To further demonstrate the contribution of SMAD3 on CCR5 regulation, we inhibited SMAD3 by pretreating breast cancer cells with SIS3, a known SMAD3 inhibitor, in the luciferase assay." (PMID 29299159, 2017). "After treating the two breast cancer cell lines with SB431542, a TGFβ type I receptor inhibitor that specifically inhibits SMAD2 and SMAD3 phosphorylation, which leads to down regulation of DNMT1 and upregulation of CLDN6." (PMID 28867761, 2017). "Snail1 has previously been reported to interact with the R-Smad, Smad3 and co-Smad, Smad4 to drive EMT in breast carcinomas." (PMID 29228645, 2017). "TGFβ1-activated TBX3 protein expression is mediated by Smad3/4 and TBX3 is overexpressed in several cancers, including breast cancer." (PMID 27863437, 2016). "Inhibition of Smad3/2 enhances tumorigenicity of human MCF10CA1h (low grade, invasive) breast cancer cell line, which is derived from the MCF10A cells; whereas overexpression of Smad3 reduces tumorigenicity." (PMID 27588495, 2016). "Another member of the NF- κB related factors family is RelA which is found to collaborate with SMAD3, AHR and c-Myc each of which is known to be involved in breast cancer." (PMID 26627005, 2015). "Breast cancer cell motility and migration is driven by sub-populations of cells with dynamic TGF-β-Smad3 activity." (PMID 25744371, 2015).
breast carcinoma (continued). "Previous results have demonstrated that SMAD3 and SMAD4 are critical for TGF-β-induced EMT and the metastasis of breast cancer cells." (PMID 25970785, 2015). "A previous study demonstrated that Smad3 and -4 had important roles in TGF-β-induced epithelial to mesenchymal transition and breast cancer metastasis." (PMID 25376731, 2015). "Here, we show that MSCs are able to increase both Smad3 and CREB phosphorylation in breast cancer cells suggesting that MSCs are able to induce the TGFβ and cAMP pathway at the same time allowing these pathways to communicate." (PMID 23349840, 2013). "Triple-negative breast cancers, to which MDA-MB-231 cells belong, show higher metastatic potential, when the TGFβ/Smad3 pathway is more active." (PMID 23349840, 2013). "Barcode validation results for differential over-expression of MEF2C, SMAD3 and POU2AF1 within two platforms for several gene-probes in different breast cancer tissues." (PMID 22952604, 2012). "We found p21 to physically interact with Smad3 and the histone acetyltransferase p/CAF in response to TGFβ and identified p21 and p/CAF as key regulators of TGFβ-mediated breast cancer cell migration and invasion." (PMID 22995475, 2012). "Furthermore, the aberrant expression may be a mechanism that reconciles the allelic imbalance often associated with the 15q21 locus in breast cancer with the apparent lack of SMAD3 inactivating mutations." (PMID 21835029, 2011). "This study has demonstrated that expression levels of SMAD3 and SMAD4 are important factors in breast cancer but have different consequences." (PMID 21835029, 2011). "The peptidoglycan of Staphylococcus aureus (PGN-SA) triggered breast cancer cell TLR2 with NF-κB, STAT3 and Smad3 activation contributing to the cancer cell invasiveness and adhesiveness." (PMID 20520770, 2010). "Taken together, high level TLR2 expressed in metastatic human breast cancer cells and mediated a bacterial component, PGN, to stimulate NF-κB activity resulting in STAT3 and Smad3 sequential activation, which contributed to invasiveness and adhesiveness." (PMID 20520770, 2010). "This study provides evidence that the SMAD3 gene, which encodes a key regulatory protein in the transforming growth factor beta signalling pathway and is known to interact directly with BRCA2, may contribute to increased risk of breast cancer in BRCA2 mutation carriers." (PMID 21114847, 2010). "In the presence of TGF-β1, H2O2 increased the BRCA1 and Smad3 interaction at the endogenous level in human keratinocyte HaCaT cells and wild type BRCA1-reconstituted HCC1937 breast cancer cells (HCCBRCA1)." (PMID 19768112, 2009). "Moreover, ginkgetin treatment upregulated miR-122-5p, leading to specific binding to the GALNT10 3′-untranslated regions, which ultimately reduced Smad3 mRNA and protein levels in MDA-MB-231 breast cancer cells." (PMID 40762894, 2025). "In breast cancer cells, inhibition of the Smad3/4 complex binding to the B3GALT4 promoter SBE can lead to the down-regulation of the B3GALT4 gene expression, which in turn hinders the epithelial-mesenchymal transition process in breast cancer cells." (PMID 40718832, 2025). "In addition, SMAD3, SMAD6, and SMAD7 were lowly expressed in stage II breast cancer, while SMAD4 and SMAD2 were lowly expressed in stage III cancer." (PMID 38514720, 2024). "In support of this hypothesis, in breast cancer, THBS2 was found to promote cell invasion by activating the PI3K/AKT signaling pathway, while THBS1-induced breast cancer cell invasion occurs by the YAP/FAK and transforming growth factor (TGF)-beta/Smad3 axes." (PMID 38339060, 2024). "In addition, we confirmed that SMAD3 knockdown had synergistic effects on BAY-1161909- and XK-469-induced apoptosis of breast cancer cells." (PMID 38514720, 2024).
breast carcinoma (continued). "Thus, in this study, we established the interactome of Smad3 using immunoprecipitation mass spectrometry (IP‐MS) and characterized the cofactors in MDA‐MB‐231 breast cancer cells with lung metastatic potential." (PMID 39225541, 2024). "SMAD3 and SMAD5 were overexpressed in all types of breast cancer, which could be related to the reduced expression of miR-145, and the findings for SMAD4 and miR-155 were similar." (PMID 39337574, 2024). "Narasin inhibits TGF‐β/SMAD3 and IL‐6/STAT3 activation in breast cancer cells." (PMID 37864240, 2023). "In human breast cancer cells (MCF-7), EA inhibited cell proliferation and halted the cell cycle at the G0/G1 phase via an increase in p21 induced via overexpression of a signal molecule called mothers against decapentaplegic homolog 3 (Smad3)." (PMID 38002335, 2023). "Earlier studies have identified the downregulation of the TGF-β/Smad3 signaling pathway as a critical factor contributing to the inhibition of cell proliferation and the induction of cell cycle arrest in EA-treated MCF-7 breast cancer cells." (PMID 38002335, 2023). "As quantified by luciferase assay, non-malignant MCF10A breast cells and poorly-invasive MCF7 breast cancer cells treated with recombinant human TGF-β1 (rhTGF-β1) showed low TGF-β/SMAD3 signaling activity." (PMID 38105247, 2023). "We identified an increased presence of phosphoproteins such as p-AKT1, p-STAT3, p-SMAD3, p-CREB1, p-p38, p-PTN11, and p-ERK1 in mammary tumors compared to the mammary gland, which should be further investigated as potential novel biomarkers in mammary carcinogenesis." (PMID 37568820, 2023). "Studies from breast cancer cells showed that SOX4 is a downstream of Transforming growth factor beta (TGFβ) signaling and that SOX4 expression was required for TGFβ-mediated induction of a subset of SMAD3/SOX4-co-bound genes." (PMID 35529852, 2022). "Moreover, the promoting effect of GluOC was reversed in MDA-MB-231 breast cancer cells treated with specific inhibitor of SMAD3 (SIS3), a SMAD3 phosphorylation inhibitor." (PMID 35413833, 2022). "In breast cancer, tumor cells often secrete excess TGF-β protein, forming Smad3/Smad4 complexes in the nucleus, which increases the expression of SLUG protein and promotes tumor invasion, and knockdown of Smad3 protein reduces tumor invasion and metastasis." (PMID 35251569, 2022). "Overall, these results suggest that the SMAD3-dependent gene signature is present in hypoxic tumors and that VIM and ITGB2 are better predictors of metastasis or cancer recurrence in lung carcinoma and breast cancer than RHOB." (PMID 35681731, 2022). "Our findings demonstrated that lotus leaf alcohol extract inhibits the cell migration and metastasis of ER− breast cancer, at least in part, via TGF-β1/Erk1/2 and TGF-β1/SMAD3 signaling pathways, which provides a potential therapeutic strategy for ER− breast cancer." (PMID 33602253, 2021). "However, the TFs such as KLF5 (52%), KLF1 (39%), and SMAD2::SMAD3::SMAD4 (31%) showed significant enrichment (q < 0.1) in gained peaks and FOX family of TFs (FOXA1 28%, FOXA2 28% and FOXF2 17%) in lost peaks in breast carcinomas." (PMID 34090364, 2021). "To determine the clinical relevance of CCL2/CCR2 signaling protein expression in breast cancer, we performed immunohistochemistry staining on patient samples of DCIS, IDC and normal adjacent tissues for detection of CCL2, CCR2, phospho-SMAD3 and phospho-42/44MAPK proteins." (PMID 33888841, 2021). "Finally, by comparing the expression patterns of components of the TGF signaling pathway and KDM7A in human breast cancer specimens, we discovered that there was statistically significant correlation between KDM7A and TGFB2/SMAD2/SMAD3/SMAD4." (PMID 34249916, 2021).
breast carcinoma (continued). "Given that both KAT6A and TGF‐β/SMAD3 are activated in many cancers, including breast cancer, we investigated potential crosstalk between these two intensively studied oncogenic pathways and determined the biological consequence of the KAT6A–SMAD3 signaling in TNBC metastasis." (PMID 34392614, 2021). "TGF-β increases the expression of the Nox4 gene, which contributes to ROS production through a Smad3-dependent mechanism, and it might be significant for the development of TGF-β-generated EMT in breast cancer." (PMID 34947978, 2021). "Hypomethylated SMAD3 was found in cancers of the digestive system, such as liver cancer, gastric cancer, and colorectal cancer, but not in breast cancer, endometrial cancer, and lung cancer." (PMID 33036415, 2020). "Furthermore, the knockdown of TrkB in breast cancer cells promotes TGF-β-mediated transcriptional activation through phosphorylation of SMAD2 and SMAD3." (PMID 32340410, 2020). "MiR-145 could inhibit cell invasion and migration by targeting TWIST in Colorectal Cancer, TGFBR2/Smad3 axis in bladder cancer, phospholipase C epsilon 1 in esophageal squamous cell carcinoma, ADAM19 in glioblastoma, and TGF-β1 in breast cancer." (PMID 32083506, 2020). "Because TMEPAI is a Smad dependent TGF-β target gene and Smad3 but not Smad2 deficiency reduced TMEPAI levels, we tested the effect of R-Smad deficiency on cell migration and invasion of breast cancer cells by using Boyden chamber coated with matrigel." (PMID 31798766, 2019). "In TMEPAI knockdown cells, even though both Smad2 and Smad3 activities are enriched, the growth of breast cancer cells is inhibited suggesting that Smad2 transcriptional activity is dominant and growth inhibitory over Smad3 in the absence of TMEPAI." (PMID 31798766, 2019). "Since PTEN protein levels are regulated by TMEPAI, the TGF-β –SMAD3-TMEPAI-PTEN axis may be involved in regulating both growth and motility of breast cancer cells." (PMID 31798766, 2019). "Since both Smad3 and TMEPAI knockdown had identical effect on breast cancer cell growth, we tested whether TMEPAI expression driven by Smad3 is responsible for subversion of growth and migration suppressive effects of TGF-β in breast cancer cells." (PMID 31798766, 2019). "Canonical Smad3 signaling and ERK/Sp1 signaling pathways are required for the TGF‐β‐induced upregulation of EGFR and the enhancement of migration and invasion abilities of breast cancer cells." (PMID 29215776, 2018). "To investigate whether Sp1 and Smad3 elicit a synergetic effect on TGF‐β‐induced upregulation of EGFR expression, on the basis of Smad3 knockdown, we used the Sp1 inhibitor MTM to treat breast cancer cells." (PMID 29215776, 2018). "To further confirm the role of Sp1 and Smad3 in TGF‐β‐induced enhancement of the migration and invasion abilities of breast cancer cells, we knocked down the expression of Sp1 or Smad3 using two different siRNA sequences in two breast cancer cells." (PMID 29215776, 2018). "Canonical Smad3 signaling and ERK/Sp1 signaling pathways were also crucial for the TGF‐β‐induced upregulation of EGFR expression and the enhancement of migration and invasion abilities of breast cancer cells." (PMID 29215776, 2018). "Thus, our data suggest that BMP7 induces breast cancer cell aging by a mechanism involving BMPRII receptor- and Smad3-mediated repression of the hTERT gene." (PMID 27696331, 2017). "Smad3 and Smad4 form a complex with Snail1, driving EMT in breast carcinomas." (PMID 29228645, 2017).